BDH1 (3-hydroxybutyrate dehydrogenase 1)
Synonyms: BDH; SDR9C1
Tractability: PROTAC: ubiquitination databases record sites on it; its protein half-life has been measured.
Gene: Protein-coding gene on chromosome 3 (197,509,776 to 197,573,382, reverse strand). Ensembl gene ENSG00000161267.
Subcellular location: Mitochondrion inner membrane; Mitochondrion matrix
Subcellular location (Human Protein Atlas): Mitochondria; Nucleoplasm
Pathways (Reactome):
Metabolism: Synthesis of Ketone Bodies; Utilization of Ketone Bodies
Metabolism of proteins: Mitochondrial protein degradation
Gene Ontology:
Molecular function: 3-hydroxybutyrate dehydrogenase activity; oxidoreductase activity, acting on the CH-OH group of donors, NAD or NADP as acceptor
Biological process: ketone biosynthetic process; ketone catabolic process
Cellular component: mitochondrion; matrix side of mitochondrial inner membrane; mitochondrial inner membrane; mitochondrial matrix
Genetic constraint (gnomAD): Loss-of-function variants: 30 observed, 34.24 expected, observed/expected ratio (o/e) 0.88, 90% interval 0.65 to 1.19. The upper end of that interval is the gene's LOEUF score, 1.19, which puts it in group 5 of 6, group 1 being the genes least tolerant of losing a copy. Missense variants: 443 observed, 484.1 expected, observed/expected ratio (o/e) 0.92, 90% interval 0.85 to 0.99. Synonymous variants: 190 observed, 191.58 expected, observed/expected ratio (o/e) 0.99, 90% interval 0.88 to 1.12.
Homologues: Orthologues: chimpanzee BDH1 (99% identical), macaque BDH1 (97% identical), guinea pig BDH1 (89% identical), rat Bdh1 (87% identical), mouse Bdh1 (86% identical), rabbit BDH1 (85% identical), pig BDH1 (84% identical), dog BDH1 (80% identical), tropical clawed frog bdh1a (73% identical), zebrafish bdh1 (54% identical). Paralogues in human: HSD17B6 (36% identical), RDH16 (35% identical), SDR9C7 (31% identical), DHRS9 (31% identical), RDH5 (31% identical), HSD17B2 (29% identical), HSD11B2 (27% identical), HSD17B12 (22% identical), HSD17B1 (21% identical), HSDL1 (19% identical), SDR16C5 (19% identical), HSD17B14 (18% identical), and 13 more.
Diseases named in the same sentence as BDH1 in open-access papers:
BDH1 is named in the same sentence as 61 diseases in open-access papers, as found by Europe PMC text mining. Sharing a sentence is not in itself a finding about the gene and the disease. The quoted sentences say what the papers report.
heart failure (17 papers, 2017 to 2026). Inability of the heart to pump blood at an adequate rate to meet tissue metabolic requirements. "Recapitulating previous studies that have reported increased cardiac BDH1 expression and subsequent ketone metabolism in animals and humans with heart failure, we previously observed a robust increase in BDH1 protein expression in hearts from TazKD mice." (PMID 41425248, 2025). "Heart failure (HF) mice with heart-specific BDH1 knockout exhibit more severe ventricular remodeling and dysfunction." (PMID 39512825, 2024). "Collectively, these data underscore the variability in circulating ketone availability, myocardial BDH1 protein expression, and myocardial ketone utilization that occur during heart failure." (PMID 39680452, 2024). "Among these four pathway members, Bdh1 has been reported to protect the heart from heart failure in a transverse aortic constriction mouse model." (PMID 38015723, 2023). "Heart-specific overexpression of Bdh1 has been reported to significantly ameliorate heart failure by inhibiting oxidative stress." (PMID 38015723, 2023). "The novel Bdh1 TG model provided further evidence of intervening myocardial ketone body metabolism as a potential therapeutic strategy for treating heart failure." (PMID 35283773, 2022). "In TAC-induced heart failure, Bdh1 cardiac overexpression can significantly ameliorate the pathogenesis through inhibition of oxidative stress." (PMID 35115498, 2022). "In another report, cardiac-specific BDH1 overexpression in TAC-induced heart failure prevented cardiac remodeling and DNA damage from pressure overloaded stress." (PMID 34940604, 2021). "Recent studies observed an increase in the mitochondrial β-hydroxybutyrate dehydrogenase (BDH1), which coincided with elevated plasma levels of βOHB in both rodent and human models of heart failure." (PMID 31885811, 2019). "We reveal BDH1 expression as an early biomarker of heart failure and its potential impact, through ketone signaling, on CX-43 levels in E2F6-induced DCM." (PMID 28085920, 2017). "Further, metabolic remodeling is known to occur in heart failure with enhanced BDH1 and ketone signaling." (PMID 28085920, 2017). "It was recently demonstrated that there is an increase in ketone metabolism and the ketogenic enzyme, β-hydroxybutyrate dehydrogenase 1 (BDH1), in human and mouse heart failure." (PMID 28085920, 2017). "Metabolic changes play important roles in human heart failure and studies imply the ketogenic enzyme β-hydroxybutyrate dehydrogenase I (BDH1) is a potential biomarker." (PMID 28085920, 2017). "Cardioprotection of Bdh1 overexpression in TAC-induced heart failure." (PMID 35283773, 2022). "Indeed, cardiac-specific deletion of Bdh1 in mice exacerbates cardiac dysfunction and remodeling in a heart failure model, while overexpression of Bdh1 protects against cardiac dysfunction and adverse myocardial remodeling." (PMID 34950719, 2021). "This implies that the induction of BDH1 may be an early marker for metabolic stress/changes in the myocardium that precede heart failure." (PMID 28085920, 2017). "Research showed that the expression of ketolysis-related proteins, including BDH1 and OXCT1, was increased in patients with heart failure." (PMID 32922293, 2020). "Likewise, increased cardiac ketone oxidation rates in mice with a cardiac‐specific overexpression of BDH1 led to improved cardiovascular outcomes (e.g., increased LVEF, decreased cardiac hypertrophy) in response to TAC‐induced heart failure." (PMID 40349316, 2026). "It appeared that mice without BDH1 showed worsened heart failure in response to fasting or pressure overload/ischemia compared to mice with BDH1." (PMID 37571305, 2023). "For the high expression of Bdh1 and the increased oxidation of ketone bodies in the HSD group, it may be an adaptive change in heart failure, which was also observed in other studies." (PMID 35370704, 2022).
heart failure (continued). "Given that the increased ROS plays a central and prominent role in the pathogenesis of fatty liver disease and Bdh1 have been reported to inhibit oxidative stress in heart failure, we next detected the ROS level and observed a significant increase of ROS in LO2 cells transfected with Bdh1 siRNA." (PMID 35115498, 2022). "It is interesting to note that BDH1 levels were not increased in the adult (6wk old) Tg-myocardium which are experiencing heart failure." (PMID 28085920, 2017). "In the realm of drug development, focusing on key enzymes and transporters involved in ketone metabolism, such as BDH1 and SCOT, novel therapeutics could provide more targeted and effective treatment options for heart failure patients by targeting ketone metabolism pathways." (PMID 39512825, 2024). "Notably, overexpression of Bdh1 in PA-treated LO2 cells or fatty livers could protect hepatocytes from lipotoxicity, which is consistent with the protective effect of Bdh1 in TAC-induced heart failure." (PMID 35115498, 2022).
hepatocellular carcinoma (12 papers, 2019 to 2025). A malignant tumor that arises from hepatocytes. "demonstrating heightened BDH1 activity in nutrient‐deficient human hepatocellular carcinoma cells, leading to the reactivation of ketolytic processes and subsequent cell proliferation." (PMID 38098610, 2023). "However, BDH1 expression is linked with liver cancer, acute myeloid leukaemia, and hepatocellular carcinoma." (PMID 36412907, 2022). "For instance, Zhicheng Liu and Heng Zhang have shown that BDH1 expression is positively correlated with prognosis in hepatocellular carcinoma patients." (PMID 40885386, 2025). "Indeed, Zhang and co-workers recently reported that BDH1-mediated histone Kbhb up-regulated stemness-associated genes, promoting propagation of hepatocellular carcinoma (HCC) cells." (PMID 38880495, 2024). "Under serum-starved conditions, hepatoma cells are able to express BDH1 and 3-oxoacid CoA-transferase 1 (OXCT1) as well as oxidize ketones." (PMID 36077764, 2022). "Given that Bdh1 can also mediates β-hydroxybutyrylation to regulate gene expression in hepatocellular carcinoma stem cells, continued studies aimed at identifying new mechanisms mediated by Bdh1 in MAFLD are desperately needed." (PMID 35115498, 2022). "Downregulation of BDH1 is a prognostic marker in hepatocellular carcinoma." (PMID 40165902, 2025). "Given that the mRNA expression of BDH1 could be transcriptionally regulated by MTA2-triggered R-loop in hepatocellular carcinoma stem cells, we hypothesized that HG- and PA-induced BDH1 reduction might be mediated by MTA2." (PMID 38015723, 2023). "In hepatocellular carcinoma, BDH1 has been shown to regulate H3K9bhb modification." (PMID 38098610, 2023). "Inhibition of BDH1, as previously reported, results in increased levels of H3K9bhb, consequently upregulating the expression of multiple genes and fostering the proliferation of hepatocellular carcinoma cells." (PMID 38098610, 2023). "Moreover, Bdh1-mediated β-hydroxybutyrylation potentiates propagation of hepatocellular carcinoma stem cells." (PMID 35115498, 2022). "However, inhibition of BDH1 resulted in the aggregation of BHB and the increase of H3K9bhb, which promoted the proliferation of hepatocellular carcinoma stem cells." (PMID 36172354, 2022).
glioma (8 papers, 2014 to 2025). A benign or malignant brain and spinal cord tumor that arises from glial cells (astrocytes, oligodendrocytes, ependymal cells). "Low expression levels of ketolytic enzymes, including BDH1, have been found in tumors such as pancreatic cancer and gliomas." (PMID 34150668, 2021). "Accordingly, a recent study showed that the expression levels of the ketone body-metabolizing enzymes succinyl-CoA 3-oxoacid CoA transferase (OXCT1) and 3-hydroxybutyrate dehydrogenase 1 (BDH1) are reduced in glioma tissue." (PMID 24728273, 2014). "mRNA expression of OXCT1 and BDH1 was significantly lower in gliomas compared to normal brain." (PMID 33420169, 2021). "In a recent clinical trial, differential expression of ketolytic enzymes (including BDH1 and OXCT1) was described in gliomas." (PMID 31399389, 2020). "Several reports have suggested that cancer cells, such as glioma cells, are unable to metabolically utilize ketone bodies because of the absence of BDH1." (PMID 41465202, 2025). "The authors hypothesized that patients with low or very low expression of BDH1 and OXCT1 in malignant gliomas may respond better to KD therapy than patients with gliomas that express higher levels of ketolytic enzymes." (PMID 31399389, 2020).
diabetes (6 papers, 2023 to 2026). "In patients with T2D and atherosclerosis, vascular expression levels of BDH1 are decreased, which is consistent with decreased BDH1 expression in the aorta from diabetes-induced atherosclerosis and ApoE−/− mice models." (PMID 39198360, 2025). "Transcriptomic analysis in patients with Type 2 diabetes mellitus and HF confirmed the suppression of BDH1 and OXCT1 gene expression in the heart, which is consistent with findings in mouse models." (PMID 40458087, 2025). "Western blot validation of several proteins with high pathophysiological importance, including MYH7, HMGCS2, PDK4, and BDH1, indicated that mass spectrometry was able to qualitatively, but not quantitatively, reflect the fold changes of certain proteins in diabetes." (PMID 39539089, 2024). "Again, stratification by sex revealed significantly higher Bdh1 expression in the male offspring exposed to maternal diabetes + HFD compared to their healthy male counterparts (p = 0.041), while Bdh1 expression in the female offspring was not different between groups (>0.999)." (PMID 36835096, 2023). "We found that BDH1 is downregulated in the kidneys in DKD mouse models, patients with diabetes, and high glucose- or palmitic acid-induced human renal tubular epithelial (HK-2) cells." (PMID 38015723, 2023). "Overall, sex-related differences in Hmgcs2 and Bdh1 expression are found only in diabetes + HFD-exposed myocardium, but not in controls." (PMID 36835096, 2023). "To determine the effects of maternal diabetes + HFD on levels of enzymes needed for ketone body metabolism, we examined the gene expression of 3-hydroxy-3-methylglutaryl-CoA synthase 2 (Hmgcs2) and β-hydroxy butyrate dehydrogenase (Bdh1) in neonatal myocardium." (PMID 36835096, 2023).
lung carcinoma (6 papers, 2018 to 2025). "We found that 3‐hydroxybutyrate dehydrogenase 1 (BDH1) was associated with proliferation and metastases of lung cancer." (PMID 36919822, 2023). "Firstly, the mRNA expression of BDH1 was associated with lymph node metastases of lung cancer by our transcriptome sequencing data and TCGA data set." (PMID 36919822, 2023). "Three genes (BDH1, DDX49 and EGFR) were associated with lymph node metastases of lung cancer, and BDH1 gene had a highest predictive capacity for lymph node metastases and distant metastases through multivariate logistic regression." (PMID 36919822, 2023). "BDH1 expression in both tissue and serum samples was associated with lung cancer metastases." (PMID 36919822, 2023). "Our results found that BDH1 was an important gene for lymph node metastases and distant metastases of lung cancer, and BDH1 knockdown reduced cell proliferation, migration and invasion." (PMID 36919822, 2023). "PARP1‐mediated activation of AMPK‐mTOR signalling pathway plays an essential role in BDH1‐induced autophagy in lung cancer cells." (PMID 36919822, 2023). "Taken together, serum BDH1 was a useful biomarker for the lymph node metastases and distant metastases of lung cancer." (PMID 36919822, 2023). "To explore the role of BDH1‐induced autophagy in proliferation and metastases in lung cancer cells, we treated PC‐9 cells with rapamycin and lentivirus transfection." (PMID 36919822, 2023). "Among the 66 lung cancer patients, the serum concentration of BDH1 was significantly higher in patients with metastases than that in those without any metastases (median [IQR]: 311.5 [243.3–388.4] ng/mL vs. 104.7 [164.3–205.8] ng/mL, p < 0.001)." (PMID 36919822, 2023). "We identified BDH1 gene through a series of strict process, including four independent cohorts, functional verification in two kinds of lung cancer cell lines and a series of cell function experiments." (PMID 36919822, 2023). "Secondly, knockdown of BDH1 decreased proliferation, migration and invasion in lung cancer cell lines." (PMID 36919822, 2023). "In the study, we integrated transcriptome sequencing data of our clinical samples and an independent sample from TCGA data set of lung cancer with metastases to find 3‐hydroxybutyrate dehydrogenase 1 (BDH1) gene." (PMID 36919822, 2023). "In order to uncover the relationship between BDH1‐induced autophagy and lung cancer progression, PC‐9 cells were treated with 10 mM rapamycin and siBDH1." (PMID 36919822, 2023). "There was a significant correlation between mRNA of BDH1 expression and distant metastases of lung cancer." (PMID 36919822, 2023). "Thus, we believed that the BDH1 as potential biomarker for predicting lymph node metastases in lung cancer patients is reliable." (PMID 36919822, 2023). "Furthermore, BDH1 expression in both tissue and serum was an important predictive biomarker of lymph node and distant metastases of lung cancer." (PMID 36919822, 2023). "BDH1 was upregulated in cancer and could serve as a critical therapeutic target for metastases of lung cancer." (PMID 36919822, 2023). "Moreover, high expression of BDH1 induced autophagy and subsequently proliferation and migration in lung cancer cells." (PMID 36919822, 2023). "Our data suggested that the serum BDH1 was an important biomarker for metastases of lung cancer." (PMID 36919822, 2023). "Moreover, BDH1 can induce autophagy and subsequent proliferation and migration in lung cancer cells." (PMID 36919822, 2023). "In addition, the discriminative capacities of BDH1 gene were validated by ROC analysis in three independent cohorts from patients with lung cancer." (PMID 36919822, 2023). "Our findings demonstrated high endogenous expression of BDH1 in several lung cancer cell lines." (PMID 38098610, 2023). "We also examined H1229 lung cancer cells with low expression of BDH1 and OXCT1." (PMID 29414764, 2018).
lung carcinoma (continued). "Taken together, these findings suggested that BDH1 might be a useful novel biomarker and therapeutic target for lung cancer metastases, and that PARP1‐mediated AMPK‐mTOR signalling pathway played a critical role in BDH1‐induced autophagy, proliferation and metastases." (PMID 36919822, 2023). "Our finding not only suggested that BDH1 might be useful as a novel biomarker and therapeutic target for lung cancer metastases, but also imply that PARP1‐mediated AMPK‐mTOR signalling pathway might play a critical role in BDH1‐induced autophagy and lung cancer proliferation and metastases." (PMID 36919822, 2023). "In the future, BDH1 might be a useful biomarker for the diagnosis and therapy of lung cancer." (PMID 36919822, 2023). "Although no rigorous validation set was included into the analysis, a series of functional verification in cell lines and reproducible results from the tissue and serum samples could demonstrate that BDH1 was an important biomarker of metastases of lung cancer." (PMID 36919822, 2023). "Taken together, these findings suggested that BDH1 might be a useful novel biomarker and therapeutic target for lung cancer metastases, and that PARP1‐mediated AMPK‐mTOR signalling pathway might play a critical role in BDH1‐induced autophagy, proliferation and metastases." (PMID 36919822, 2023). "BDH1 might be a novel therapeutic target for advanced stage lung cancer." (PMID 36919822, 2023). "In lung cancer, PARP1 activates the AMPK–mTOR pathway → enhances BDH1‐mediated autophagy → promotes cell proliferation/metastasis; BDH1 overexpression accelerates in vivo tumor growth." (PMID 40904702, 2025). "In lung cancer, PARP1 mediates the AMPK–mechanistic target of rapamycin (mTOR) pathway, which regulates autophagy induced by β‐hydroxybutyrate dehydrogenase 1 (BDH1)." (PMID 40904702, 2025). "To delve deeper into the role of BDH1 in LUAD, we selected six lung cancer cell lines and HBE cells to measure BDH1 expression levels." (PMID 38098610, 2023). "Consistently, ketolytic enzyme expression levels, such as BDH1 and SCOT, are low or undetectable in pancreatic cancer (PANC-1), lung cancer (H1299), and neuroblastoma (SK-N-AS) human cell lines as well as in human glioblastoma in vivo." (PMID 34829786, 2021). "In addition, BDH1, through activating PARP1‐mediated AMPK‐mTOR signalling pathway promoted lung cancer progression." (PMID 36919822, 2023). "It was unknown whether BDH1 promoted the proliferation, migration and invasion of lung cancer cells through some signalling pathways independent of its role in ketone body metabolism." (PMID 36919822, 2023).